HMGB1 (high mobility group box 1)
Diseases named in the same sentence as HMGB1 in open-access papers (continued):
Sharing a sentence is not in itself a finding about the gene and the disease.
pancreatic cancer (continued). "Another study suggests that intracellular HMGB1 is a novel tumor suppressor of pancreatic cancer, adding support to our hypothesis that HMGB1 plays an antitumor role." (PMID 30744691, 2019). "Therefore, we are interested if dying pancreatic cancer cells during radiotherapy activate HMGB1-mediated paracrine signaling events that promote dedifferentiation of resident non-CSCs." (PMID 31558702, 2019). "Serum levels of AGE and HMGB1 are elevated in pancreatic cancer patients." (PMID 29529089, 2018). "Taken together, these results indicate that dying-cell-derived HMGB1 may promote pancreatic cancer metastasis." (PMID 29615080, 2018). "However, the precise mechanisms for HMGB1 regulating pancreatic-cancer metastasis are still to be elucidated." (PMID 29615080, 2018). "Moreover, HMGB1-induced pancreatic cancer cells’ invasion and metastasis was mediated by the receptor for TLR2, rather than TLR4 or RAGE." (PMID 29615080, 2018). "Thus, inhibiting HMGB1 release or knocking down HMGB1 increases chemotherapy sensitivity in leukemia or pancreatic cancer cells." (PMID 29636841, 2018). "Therefore, we are interested if dying pancreatic-cancer cells undergoing apoptosis during radiotherapy activate HMGB1-mediated paracrine signaling events that promote the migration of surviving tumor cells." (PMID 29615080, 2018). "We suggest a strategy to inhibit HMGB1 for preventing pancreatic carcinoma relapse and metastasis." (PMID 29615080, 2018). "To determine whether HMGB1 expression is aberrant in human pancreatic cancer, we used pancreas tissue microarrays to analyze a cohort of 90 patients with pancreatic cancer." (PMID 28374746, 2017). "Furthermore, RAGE is similarly required for HMGB1-induced alterations in bioenergetics and nuclear DNA-HMGB1-histone complex-induced cell death in pancreatic cancer cells and macrophages." (PMID 27623211, 2016). "Moreover, HMGB1/RAGE interaction plays an important role in mitochondrial function in pancreatic tumor cells, including ATP production." (PMID 26854151, 2015). "We postulate that plasma HMGB1 concentration after treatment could also be used as a marker for predicting therapeutic response to Gem/PX-478 in patients with pancreatic cancer." (PMID 25544770, 2015). "Recent in vitro studies with pancreatic cancer cells revealed that the targeted knockout or inhibition of HMGB1 and RAGE could increase apoptosis and suppress pancreatic cancer cell growth." (PMID 21106117, 2010). "It has been recently observed that pancreatic tumor cells increase autophagy and release HMGB1 in response to chemotherapy, radiation, and hypoxia, which may promote tumor cell survival." (PMID 21106117, 2010). "Furthermore, we found that the supplementation of HMGB1 could alleviate the inhibition of ferroptosis by METTL3 in pancreatic cancer." (PMID 40495163, 2025). "However, the association of dying-cell derived HMGB1 and EMT in pancreatic-cancer metastasis has rarely been investigated, and the underlying molecular mechanism remains unclear." (PMID 29615080, 2018). "Indeed, we found that glycyrrhizin treatment prevented PanIN development preserving normal acinar structures, sustaining nuclear HMGB1 expression, and decreasing circulating HMGB1 and nucleosome levels in the cerulein-mediated accelerated oncogenic K-Ras mouse model of pancreatic cancer." (PMID 28374746, 2017). "Moreover, increased cell proliferation was observed in isolated metastatic or invading tumor cells from lung (but not liver or kidney) compared to HMGB1-deficient primary pancreatic tumor cells." (PMID 28374746, 2017). "Another pathway that can be engaged by the HMGB1/RAGE axis is PI3K/Akt, as it contributes to gemcitabine resistance in pancreatic cancer by promoting protective autophagy and upregulating the expression of the multidrug resistance protein MDR1." (PMID 41465435, 2025).
pancreatic cancer (continued). "Additional regulators such as pirin (PIR) exert similar control, as PIR depletion enhances HMGB1 cytosolic translocation and activates Beclin1-ACSL4 autophagic machinery to potentiate ferroptosis in pancreatic cancer." (PMID 41465435, 2025). "In human pancreatic cancer cells and tumors, it has been demonstrated that both RAGE ligands, HMGB1 and S100P, stimulate RAGE." (PMID 38529373, 2024). "To test this, we stimulated cells with RAGE ligands observed to be upregulated in human pancreatic cancer, including S100P, S100A2, and HMGB1." (PMID 39796649, 2024). "Further experiments reveal that lucidone significantly inhibits the protein levels of HMGB1 and RAGE in GEM-resistant pancreatic cancer cells." (PMID 38529373, 2024). "Consistent with prior literature, we observed significantly elevated levels of RAGE ligands—HMGB1, S100A2, and S100P—in both human and murine pancreatic cancer cell lines relative to normal pancreatic tissue." (PMID 39796649, 2024). "Studies have shown that HMGB1 activates RAGE to affect the NF-κB signaling pathway by reducing p65 phosphorylation levels, promoting pancreatic cancer metastasis, and inducing chemoresistance to gemcitabine." (PMID 38529373, 2024). "Experiments have also demonstrated that silencing HMGB1 increases the expression of cleaved PARP, an apoptosis marker, in pancreatic cancer cells with downregulated RAGE expression, further promoting apoptosis." (PMID 38529373, 2024). "Recent study has demonstrated that HMGB1 triggered both YAP and HIF-1α nuclear translocation and enhanced YAP and HIF-1α interaction promoting pancreatic cancer stemness." (PMID 36594102, 2023). "We therefore examined the metastasis of pancreatic cancer cells in nude mice by injecting 1 × 106 Panc-1 cells cultured with PBS, N-S, HMGB1−/−-S, N-S + EP, or rhHMGB1 (150 ng/ml) into the mouse tail vein." (PMID 29615080, 2018). "In the present study, HMGB1/TLR2, dependent on the PI3K/Akt signaling pathways, induces pancreatic cancer cells’ EMT and metastasis." (PMID 29615080, 2018). "ROS can increase the release of HMGB1 from necrotic cells and then activates Beclin-1-dependent autophagy by binding to AGER in pancreatic cancer cells." (PMID 25197670, 2014). "Critically, co-inhibition of both RAGE and TLR4 was required to disrupt this autophagic response, effectively sensitizing pancreatic cancer to IRE and underscoring the complexity and therapeutic relevance of extracellular HMGB1 signaling in treatment resistance." (PMID 41465435, 2025). "Additionally, we discovered that METTL3 promotes HMGB1 degradation through a m6A-YTHDF2-dependent pathway, inhibits ferroptosis in pancreatic cancer cells, and confers resistance to gemcitabine treatment." (PMID 40495163, 2025). "Additionally, our study reveals that a combination therapy targeting HMGB1, along with gemcitabine and the ferroptosis inducer RSL3, effectively suppresses pancreatic cancer development." (PMID 40495163, 2025). "Analysis of protein expression data from the Proteomic Data Commons database revealed a negative correlation between YTHDF2 and HMGB1 protein expression in pancreatic cancer samples." (PMID 40495163, 2025). "In addition to RAGE expression, the expression of the RAGE ligands HMGB1, S100A2, and S100P was significantly upregulated in both human and murine pancreatic cancer cell lines when compared to normal pancreas." (PMID 39796649, 2024). "In a different study, using an in vivo model of murine pancreatic cancer, we showed that blocking the activation of RAGE using a RAGE-specific monoclonal antibody significantly reduced the protein levels of HMGB1 in tumors, suggesting that RAGE regulated the expression of HMGB1 in pancreatic cancer." (PMID 37627239, 2023). "Previous studies confirmed that HMGB1 could upregulate the ERK1/2 pathway in CRC, and Wnt and ERK signaling pathways were activated by HMGB1 in pancreatic cancer." (PMID 36709284, 2023).
pancreatic cancer (continued). "In human pancreatic cancer, lncRNA ZEB2-AS1 could affect cancer cell growth and invasion by regulating the miR-204/HMGB1 axis." (PMID 36420274, 2022). "In patients with pancreatic cancer, the mechanism of action of HMGB1 is not yet fully understood, although it seems to have a dual action." (PMID 34445745, 2021). "Unlike extracellular HMGB1 that promotes tumor growth, intracellular HMGB1 can regulate autophagy and mitophagy to inhibit the development of pancreatic cancer." (PMID 33262988, 2020). "We conclude that X-ray irradiation induces CD133− pancreatic cancer cell dedifferentiation into a CSC phenotype, and inhibiting HMGB1 may be a strategy to prevent CSC enrichment and further pancreatic carcinoma relapse." (PMID 31558702, 2019). "Using an in vitro coculture model, X-ray irradiation induced dying cells to release HMGB1, which further promoted CD133− pancreatic cancer cells regaining stem cell traits, such as higher sphere forming ability and expressed higher level of stemness-related genes and proteins." (PMID 31558702, 2019). "Furthermore, dying cell derived HMGB1 activates TLR2/YAP/HIF-1α pathways and induces neighboring CD133− pancreatic cancer cells dedifferentiation, which is an important signaling event underlying tumor relapse following radiotherapy." (PMID 31558702, 2019). "In addition, extracellular HMGB1 induces autophagy via its receptor RAGE in colorectal and pancreatic cancer cells." (PMID 30258050, 2018). "In summary, our results suggest that combining radiotherapy and an HMGB1 inhibitor, or targeting TLR2, may be considered a new therapeutic strategy to avoid pancreatic-carcinoma relapse and distant metastasis." (PMID 29615080, 2018). "However, whether HMGB1 can be targeted to inhibit GEM resistance and promote ferroptosis for inhibiting the development of pancreatic cancer remains unexplored." (PMID 40495163, 2025). "By regulating PIR expression, MCP exerts dual biological effects: it induces ferroptosis in pancreatic cancer cells by suppressing GPX4 and promotes macrophage pro‐inflammatory M1‐like polarization by enhancing cytoplasmic translocation and the early release of HMGB1." (PMID 38593415, 2024). "Moreover, exogenous HMGB1 can activate p-GSK 3β through the Wnt signaling pathway, upregulate the expression of Bcl-2 and Ki67, and downregulate the expression of E-CA in pancreatic cancer cells, thus fostering the proliferation of pancreatic cancer cells." (PMID 37897664, 2024). "However, the animal model used by the authors does not express functional S100P, suggesting that HMGB1 activation of RAGE can stimulate pancreatic cancer cells and promote their proliferation." (PMID 38529373, 2024). "Furthermore, the iron-binding nuclear protein pirin (PIR) can hijack HMGB1 in the nucleus, thereby inhibiting the translocation of HMGB1 to the cytoplasm and subsequent activation of beclin 1 (BECN1)-dependent autophagy and ferroptosis in pancreatic cancer cells." (PMID 36845736, 2023). "To further determine whether HMGB1 is a marker predicting cell sensitivity to cuproptosis, we examined the relationship between HMGB1 release and ES-Cu–induced cell death in MIA PaCa2 (a human pancreatic cancer cell line) cells and mouse embryonic fibroblasts (MEFs)." (PMID 36211458, 2022). "Additionally, HMGB1 derived from tumor cells or TME could promote the CSCs phenotype in lung, colon, pancreatic cancer cells." (PMID 33614649, 2021). "However, when HMGB1 was over-expressed at the same time, the activity of PANC-1 and BxPC-3 cells was partially restored, and over-expression of HMGB1 suppressed the effect of miR-181a on pancreatic cancer cells." (PMID 34374662, 2021). "Interestingly, contrary to its above results, miR-181a was significantly lower in both pancreatic cancer tissues and cell lines, which indicate that miR-181a may be regulated by ANRIL, which promotes the expression of HMGB1." (PMID 34374662, 2021).
pancreatic cancer (continued). "To connect our discovery to clinical application, using the pancreatic carcinoma patient tissue specimen, we performed immunehistochemical staining on serial sections to access the location and expression level of Caspase-3, a dying cancer-cell marker, MMP-9, a tumor-metastasis marker, and HMGB1." (PMID 29615080, 2018). "Additionally, treatment of pancreatic cancer and 938-mel cell lines with the FLT3L-expressing OV elevated ATP levels but did not affect HMGB1 release." (PMID 40955425, 2025). "GEM increased the expression of CRT on the surface of pancreatic tumour cells and enhanced the uptake of PANC-1 cells into DC but could not induce the expression of ATP or HMGB1 from the cell lines studied." (PMID 32661823, 2021). "To dissect the effects of TLR activation, we treated two of the established pancreatic cancer cell lines (BxPC-3 and MIAPaCa-2) and one primary pancreatic cancer cell line (PaCaDD135) with TLR specific ligands (LTA for TLR2, LPS for TLR4, ODN for TLR9) and a non-specific ligand (HMGB1)." (PMID 27941651, 2016).
Cognitive impairment (76 papers, 2015 to 2026). Abnormal cognition is characterized by deficits in thinking, reasoning, or remembering. "The release of HMGB1 has been associated with cognitive impairments in diabetes-related dementia, depression, and Alzheimer’s disease." (PMID 38826566, 2024). "Studies have shown that HMGB1 mediates synaptic loss and cognitive impairment in animal models of SAE6." (PMID 38734709, 2024). "Collectively, these findings underscore the robust association between heightened HMGB1 burden and an increased vulnerability to developing cognitive deficits following acute ischemic stroke." (PMID 38708343, 2024). "The study revealed a direct proportional association between HMGB1 concentrations and the incidence of cognitive dysfunction, with elevated levels correlating to a heightened probability of experiencing cognitive deficits." (PMID 38708343, 2024). "The continuous activation of neuroinflammation markers such as NOD-, LRR, pyrin domain-containing protein 3 (NLRP3), and high-mobility group box 1 (HMGB1) has been shown to be associated with cognitive impairment in NLRP3-knockout mice after TBI." (PMID 39063593, 2024). "As a member of DAMPs, high mobility group box 1 (HMGB1) has been identified as a major neuroinflammatory biomarker associated with cognitive impairments." (PMID 36776829, 2023). "The results showed that HMGB1, UA, HbAlc, years of education and history of hypertension were strongly associated with the occurrence of cognitive impairment in patients with CSVD (P < 0.05)." (PMID 37424630, 2023). "HMGB1 causes neuroinflammation and cognitive impairment through direct binding to advanced glycation end products (RAGE) and Toll-like receptor 4 (TLR4)." (PMID 36552192, 2022). "For example, human plasma HMGB1 levels were associated with mild cognitive deficits and reduced cortical thickness." (PMID 34208101, 2021). "Surgery is associated with an increase in peripheral IL-6 and HMGB1 and with cognitive impairment 6 weeks postoperatively." (PMID 33187477, 2020). "Increased brain HMGB1 levels have been associated with cognitive deficits, effects that are mediated through both TLR4 and RAGE receptors." (PMID 30687006, 2018). "In rodents, elevations of HMGB1 are associated with cognitive deficits, which can be mitigated in the presence of HMGB1 inhibitors." (PMID 30705643, 2018). "HMGB1 is generated after tissue damage, recurrent seizures, and inflammation and remains increased long after a severe systemic inflammatory insult, causing hippocampal inflammation and cognitive impairment in experimental mice." (PMID 39466324, 2025). "However, no alteration of HMGB1 was found in AUD patients during abstinence or associated with cognitive impairment, a finding that contrasts with the elevated HMGB1 concentrations in AD patients and AD patients with cognitive impairment." (PMID 38535924, 2024). "HMGB1 showed a dose-dependent relationship with risk of cognitive impairment." (PMID 38708343, 2024). "Moreover, HMGB1 has been implicated in the pathogenesis of cognitive impairments across a spectrum of neurological conditions, including epileptic disorders, Alzheimer’s disease, and various other neurodegenerative processes." (PMID 38708343, 2024). "Similarly, animal studies have shown that HMGB1 is mechanistically linked with cognitive deficits after surgery." (PMID 37106766, 2023). "Therefore, this study aimed to investigate the mechanism of HMGB1 underlying cognitive impairment in SAE." (PMID 36906561, 2023). "Here, we found that GZ reduced p-tau and HMGB1 levels simultaneously in spatial memory-associated regions, the hippocampus and PFC, and alleviated cognitive dysfunction, suggesting a close association between tau and HMGB1 in the development of cognitive impairment." (PMID 34539383, 2021).